ADIPOR1 (adiponectin receptor 1)
Diseases named in the same sentence as ADIPOR1 in open-access papers (continued):
Sharing a sentence is not in itself a finding about the gene and the disease.
Obesity (continued). "Plasma adiponectin levels were reduced by both maternal obesity and post-weaning HFD consumption when standardized by fat mass, while muscle AdipoR1 was also downregulated by both factors." (PMID 19606226, 2009). "Muscle AdipoR1 expression was downregulated by HFD consumption and maternal obesity (P<0.05, HFD and maternal effect)." (PMID 19606226, 2009). "It cooperates with the RNA-binding protein PTB to repress the translation of AdipoR1 by binding its 3′UTR; in genetic and dietary obesity models, upregulated miR-221 (and PTB) reduces AdipoR1 protein levels, impairing adiponectin signaling and insulin sensitivity." (PMID 41369385, 2025). "Conversely, the depletion of PTB or miR-221 restores AdipoR1 translation, suggesting that targeting PTB could rescue adiponectin signaling and ameliorate metabolic dysfunction in obesity." (PMID 40732992, 2025). "Knowledge about the AdipoR1/2 in adipose tissue in obesity and diabetes is scarce and not unambiguous." (PMID 39576482, 2025). "Taken together, these results suggest that FB3-14 intervention increased GPR41 levels associated with higher levels of butyric acid content, increased the PYY and GLP-1 levels, and upregulated the mRNA relative expression of Adipor1 and Adiporq, thereby alleviating HFD-induced obesity." (PMID 37836387, 2023). "In high fat-fed non-transgenic mice with obesity and insulin resistance, AdipoR1 gene expression was markedly reduced in heart (−70%), kidney (−80%), and liver (−90%) (all P < 0.05) as compared to low fat-fed mice." (PMID 31920982, 2019). "AdipoR1 plays an important role in the regulation of MCF7 cell growth and stabilization of the receptor, especially in an obese background, and presents a possible method of slowing obesity‐dependent breast cancer cell growth." (PMID 28676553, 2017). "It is an adipose hormone involved in the suppression of metabolic diseases, such as obesity and non-alcoholic fatty liver disease (NAFLD), by reducing lipogenesis and systemic lipid levels and enhancing fatty acid oxidation through acting on AdipoR1/2." (PMID 24279986, 2013). "On the other hand, it has been reported that obesity does not affect AdipoR1 methylation." (PMID 37240258, 2023). "We have also previously demonstrated that 6 h of adiponectin treatment in human primary myotubes derived from lean individuals increases AdipoR1 but not AdipoR2 mRNA expression, whereas myotubes derived from individuals who had obesity or obesity and diabetes did not alter AdipoR1 or AdipoR2." (PMID 36232744, 2022). "No major changes were seen in terms of adiponectin receptor 1 and UCP1 as a browning marker, a finding that is concurrent with others, particularly in clinical experiments where exercise fails to increase browning markers in adipose tissue in the context of obesity or activate brown adipose tissue." (PMID 38892984, 2024).
Insulin resistance (72 papers, 2006 to 2025). Increased resistance towards insulin, that is, diminished effectiveness of insulin in reducing blood glucose levels. "Subjects with adiponectin and AdipoR1 signaling deficiencies developed brain insulin resistance and impaired downstream insulin signaling, which mediates AD pathology." (PMID 33849621, 2021). "Nevertheless, the suppressive effect on INSR and ADIPOR1 indicated in this study deserves further research, as decreased expression of mRNA levels for these receptors has been linked to insulin resistance and diabetes in humans and animals." (PMID 27983572, 2016). "A recent report showed that disruption of AdipoR1 and AdipoR2 in mice caused the mice to be more vulnerable to insulin resistance than adiponectin-knockout mice." (PMID 24490657, 2014). "Polymorphisms in the adiponectin (ADIPOQ) gene and its receptors (ADIPOR1) have been associated with adiponectin levels, insulin resistance, and MetS phenotypes." (PMID 23306188, 2013). "Decreased levels of adiponectin and AdipoR1 in obesity may have causative roles in the mitochondrial dysfunction and insulin resistance observed in diabetes." (PMID 32478098, 2020). "A consistent phenotype of insulin resistance was observed in AdipoR1 deficient mice, however studies in which AdipoR2 was deleted have reported opposing phenotypes in terms of glucose tolerance and susceptibility to diet-induced insulin resistance." (PMID 31920962, 2019). "A small molecule agonist (AdipoRon) that binds and activates signaling through both AdipoR1 and AdipoR2 improved insulin resistance and glucose intolerance and increased the lifespan of obese mice." (PMID 38979340, 2024). "Moreover, leptin-deficient mice presented increased AdipoR1 and AdipoR2 mRNA expression, indicating low circulating adiponectin levels and defective adiponectin signaling, which have been linked to glucose metabolism deregulation, insulin resistance and diabetes." (PMID 39201365, 2024). "Release of adiponectin by exercise stimulates AdipoR1 and AdipoR2 to reduce insulin resistance and mitigate metabolic syndrome." (PMID 37964253, 2023). "The muscle-specific disruption of AdipoR1 led to insulin resistance and a decrease in mitochondrial biogenesis." (PMID 34204799, 2021). "The decrease in glucose levels in the face of reduced plasma insulin levels indicates improved insulin sensitivity, and the expression of human AdipoR1 in skeletal muscle indeed reduced insulin resistance index in mice on a high-fat diet." (PMID 33420419, 2021). "In a recent study conducted on male rats, the improvement in insulin resistance was shown to be mediated via the binding of the hormone to the adiponectin receptor 1 (AdipoR1)." (PMID 33897460, 2021). "We previously showed that orally active AdipoR agonist AdipoRon ameliorated insulin resistance and glucose intolerance in mice fed a high-fat diet, which was completely obliterated in AdipoR1 and AdipoR2 DKO (mouse R1·R2DKO) mice." (PMID 33420419, 2021). "Suppression of AdipoR1/AMPK signaling in Adipo−/− mice leads to the development of insulin resistance in the brain and subsequent development of AD pathology." (PMID 33849621, 2021). "Taken together, these findings indicated that HFD-induced oxidative stress mediates neuronal insulin resistance by impairing adipoR1/p-AMPK signaling both in vivo and in vitro." (PMID 31963819, 2020). "We found that metabolic perturbations from the chronic consumption of HFD elevated neuronal oxidative stress and insulin resistance through adiponectin receptor (AdipoR1) suppression in HFD-fed mice." (PMID 31963819, 2020). "Muscle-specific knockout of adiponectin receptor 1 (AdipoR1) results in systemic insulin resistance and hyperglycemia, resembling diabetic condition." (PMID 33379163, 2020).
Insulin resistance (continued). "We have also recently reported the lower expression of adiponectin (Locus: 3q27.3) and its receptor Adipor1 in the UM samples with monosomy-3, suggesting the occurrence of a local insulin resistance in such tumors." (PMID 32751097, 2020). "Herein, our results indicated that HFD induces biochemical or metabolic perturbations that elevated neuronal oxidative stress and brain insulin resistance through AdipoR1 suppression in HFD-fed mice." (PMID 31963819, 2020). "Our findings indicated that the consumption of HFD triggered metabolic perturbations, leading to alterations of the antioxidant system through suppression of the AdipoR1 signaling pathway that leads to neuronal insulin resistance in mouse brains." (PMID 31963819, 2020). "This is in keeping with the evidence that obesity decreases not only plasma adiponectin levels but also AdipoR1/R2 expression, thereby reducing adiponectin sensitivity and leading to insulin resistance, which in turn aggravates hyperinsulinemia." (PMID 30974901, 2019). "Both AdipoR1-null and AdipoR2-null mice exhibited similar phenotypes with both strains showing increased adiposity and insulin resistance." (PMID 31920962, 2019). "Recently, seven markers based on the BMI-sensitive pathway of insulin resistance, adipoR1, adipoR2, ObR, IRβ, IRS-1, IGF-1R, and IGF-2R, have been proposed to develop a new molecular typing system for endometrial cancer." (PMID 31440472, 2019). "Adiponectin is known to decrease hepatic insulin resistance and to attenuate liver inflammation and fibrosis through binding to AdipoR1 and AdipoR2, the latter is preferentially expressed in rodents livers." (PMID 29768504, 2018). "Our results showed that insulin resistance decreases not only plasma adiponectin levels but also adipoR1 expression which is consistent with those of previous report." (PMID 30524482, 2018). "The beneficial impact of adiponectin on metabolism and insulin resistance is enforced by the ceramidase activity of the AdipoR1 and AdipoR2 receptors." (PMID 25500563, 2014). "This study demonstrated that a reduction in plasma SFA decreased insulin resistance in carriers of the minor allele of rs266729 ADIPOQ and rs10920533 ADIPOR1." (PMID 23306188, 2013). "In patients with chronic HCV, hepatic expression of AdipoR1, and AdipoR2 appeared to be differentially regulated in the setting of hepatic insulin resistance, as measured by hepatic PEPCK expression, and in response to serum adiponectin." (PMID 23914225, 2013). "AdipoR1 and 2 double knockout mice increase the triglyceride level in the liver and exhibit insulin resistance and glucose intolerance, demonstrating that AdipoR1 and 2 regulate lipid and glucose homeostasis." (PMID 23874700, 2013). "Variations in the adiponectin receptor 1 (ADIPOR1) and diacylglycerol O-acyltransferase 2 (DGAT2) genes have been reported to be associated with fatty liver and insulin resistance in the Caucasian population." (PMID 21176169, 2010). "Furthermore, islet derived exosomes transfer Mut-Reg1cp into peripheral tissue, which then promote insulin resistance by inhibiting AdipoR1 translation and adiponectin signaling." (PMID 36302749, 2022). "Downregulation of the AdipoR1 was involved in the development of insulin resistance and diabetes." (PMID 36302749, 2022). "All the data suggest LMF-HSFx may reduce the insulin resistance in NAFLD patients through the regulation of Adiponectin-AdipoR1/2 pathways, which contribute the critical part of insulin resistance." (PMID 33809062, 2021). "Indeed, AdipoR1 and AdipoR2 were found to regulate insulin sensitivity in insulin target tissues, and are important in the pathophysiology of insulin resistance." (PMID 34395490, 2021). "Interestingly, AdipoR1 and AdipoR2 double-knockout mice have increased triglyceride levels and exhibit insulin resistance, demonstrating that AdipoR1 and AdipoR2 regulate lipid and glucose homeostasis." (PMID 34783654, 2021).
Insulin resistance (continued). "This suggests that both upregulation of AdipoR1 and AdipoR2 expression and agonism of AdipoRs could be potential targets for novel treatments for insulin resistance and type 2 diabetes." (PMID 30974901, 2019). "Simultaneous disruption of both AdipoR1 and AdipoR2 abolished adiponectin binding and actions, resulting in increased liver triglyceride content, inflammation and oxidative stress in adipose tissue, and consequent insulin resistance and glucose intolerance." (PMID 29107297, 2017). "Consistently, APN treatment in SH-SY5Y cells with insulin resistance and overexpressing Aβ induce higher pAkt levels through AdipoR1 upon insulin treatment whereas the induction was blocked by compound C, indicating APN can enhance neuronal insulin sensitivity through AMPK activation." (PMID 27884163, 2016). "Moreover, a previous study demonstrated that AdipoR1/R2 knockout mice exhibited aggravated insulin resistance through increased TG content, inflammation and oxidative stress." (PMID 22348333, 2012). "The purpose of this study was to determine whether variations in the AdipoR1 and AdipoR2 genes may contribute to insulin resistance, dyslipidemia and inflammation." (PMID 16700915, 2006). "Assuming that adiponectin receptors AdipoR1 and AdipoR2 mediate the antidiabetic and antiinflammatory effects of adiponectin, we hypothesized that genetic variation in AdipoR1 and AdipoR2 may contribute to insulin resistance, dyslipidemia, and inflammation." (PMID 16700915, 2006). "AdipoRon may improve insulin resistance by activating AdipoR1/AMPK/PGC1α signaling pathways." (PMID 36632609, 2021). "We intended to verify whether Os-pep regulates neuronal insulin resistance through AdipoR1." (PMID 33849621, 2021). "To evaluate whether impaired AdipoR1 signaling may contribute to mitochondrial dysfunction during the development of insulin resistance and type 2 diabetes, we determined mRNA expression of AdipoR1 in C57BL/6J mice subjected to 12 weeks of low fat (LFD) or high fat diet (HFD)." (PMID 31920982, 2019). "In summary, we have confirmed in this study that adiponectin can activate downstream Akt and AMPK signaling pathways only when AdipoR1 is overexpressed in islet β-cells, suggesting that adiponectin may improve insulin resistance when AdipoR1 is induced in muscle or adipose tissues." (PMID 29304075, 2018). "Although the ADIPOR1 rs1539355 was not identified functional SNP, this polymorphism was also found to be associated with reduced insulin resistance, suggesting there might be some linkage between this polymorphism and gene expression or function." (PMID 22087284, 2011). "A previous report revealed that adiponectin-induced activation of AdipoR1 stimulates AMPK signaling in the liver, reduces gluconeogenesis, and subsequently improves insulin resistance." (PMID 40332475, 2025). "Resveratrol alleviated the oxidative stress in muscle fibers via the AdipoR1-AMPK-PGC-1α pathway in pigs, while esculetin activated the AdiopR2-AMPK pathway, which was beneficial for hepatosteatosis and insulin resistance in HFD-induced obese mice." (PMID 37408227, 2023). "Positive effects have also been confirmed in vivo as osmotin through activation of the AdipoR1/2, APPL1, AMPK pathway, reduced blood glucose levels, decreased insulin resistance, and increased fatty acid oxidation and mitochondrial function." (PMID 35444544, 2022). "AdipoRon is an oral synthetic small molecular compound as it has a feasible effect on reducing insulin resistance and blood glucose tolerance in high-fat diet mice by specifically binding to APN receptors AdipoR1 and AdipoR2." (PMID 36632609, 2021). "Our findings show that Os-pep activates AdipoR1/AMPK signaling and regulates neuronal insulin resistance and insulin signaling, which subsequently rescues memory deficits in AD and adiponectin-deficient models." (PMID 33849621, 2021).
Insulin resistance (continued). "Alteration in Adiponectin receptor 1 (ADIPOR1) and Adiponectin receptor 2 (ADIPOR1) ADIPOR2 is important for development of insulin resistance in NIDDM." (PMID 30678306, 2019). "Although pioglitazone improved insulin resistance and hypothalamic leptin action in HFD-fed mice, it increased food intake via activation of the hypothalamic adiponectin receptor 1/AMP-activated protein kinase pathway." (PMID 29979770, 2018). "The genes adiponectin receptor 1, sestrin 3, KCNJ15 and G-protein coupled receptor 27 have all been described to play a role in insulin resistance, decreased insulin secretion and impaired blood glucose homeostasis." (PMID 25768297, 2015). "We have demonstrated for the first time in this study that one of these compounds, AdipoRon, acts on human AdipoR1, activates the AMPK pathway downstream, and augments the expression of mitochondria-related genes, thus improving impaired glucose tolerance and insulin resistance in vivo." (PMID 33420419, 2021). "As one of the insulin-sensitizing fatty factors, APN is secreted by fat cells to improve insulin resistance and attenuate hyperglycemia as well as impair RANKL-stimulated RAW264.7 cells through its receptors as AdipoR1, AdipoR2, and T-Cadherin and its downstream factors of cohesive protein APPL1." (PMID 36632609, 2021). "Taken together, these results showed the development of central insulin resistance in the HFD-fed mouse brains, as demonstrated by the attenuation of AdipoR1/AMPK activation, which may be the possible mechanism of Aβ deposition and the early onset of AD pathogenesis." (PMID 31963819, 2020). "In particular, mouse mutants lacking adiponectin, the ligand for AdipoR1 and AdipoR2, develop metabolic complications (glucose intolerance, insulin resistance) only when fed a high fat diet, which is analogous to the C. elegans paqr-2 mutants that show severe phenotypes when fed a SFA-rich diet." (PMID 28886012, 2017). "Moreover, the disruption of AdipoR1 and AdipoR2 almost completely abolished adiponectin binding in the liver, leading to an increase in triglyceride content, oxidative stress, and inflammation, which resulted in NAFLD and insulin resistance." (PMID 24490657, 2014).